ERBB4 (erb-b2 receptor tyrosine kinase 4)
Diseases named in the same sentence as ERBB4 in open-access papers (continued):
Sharing a sentence is not in itself a finding about the gene and the disease.
tumor (333 papers, 2004 to 2026). "Concurrently, two genes encoding neurotrophic factor receptors with tumor-suppressing effects—Ntrk1 and Erbb4—also exhibited markedly reduced expression levels." (PMID 41415031, 2025). "In tumor cells, the main intracellular pathways associated with ErbB4 are Ras-MAPK-ERK and PI3K-Akt pathways." (PMID 37800117, 2023). "ERBB4 is the only member of the ERBB family with a potential function as a tumor suppressor gene, and loss of the gene copy number of ERBB4 was found in approximately 20% of human lung squamous carcinoma and adenocarcinoma patients." (PMID 37513116, 2023). "ERBB4 encodes the epidermal growth factor receptor-4 protein and is required for normal tissue development, such as the heart and nervous system, and tumor suppression." (PMID 36836780, 2023). "The study found that a region in Intron 1 of the ERBB4 gene was deleted in 69.1% of tumor samples harboring ERBB4 copy number loss." (PMID 36119496, 2022). "The Cancer Genome Atlas (TCGA)-NSCLC cohort has been collected to explore the role of ERBB4 mutations in the tumor-infiltrating immune cells and TMB level." (PMID 34620079, 2021). "Activation of ERBB receptors is often associated with aggressive forms of tumor and poor patient prognosis, whereas ERBB4 signaling has been found to have cell growth inhibiting properties." (PMID 34068503, 2021). "The relationship between ERBB4 mutation and tumor-infiltrating immune cells was analyzed with the help of CIBERSORT algorithm." (PMID 34620079, 2021). "Acting in a cell-autonomous manner, these erbB4 variants promote the proliferation and survival of tumor cells." (PMID 31291965, 2019). "In LSCC, the altered tumor microenvironment caused by oxidative stress induced by the stimulation of NNK can potentially cause the dysregulation of ERBB4, PDPN, and EMR2 signaling pathways." (PMID 31217907, 2019). "In fact, of the 81 GBM tumor samples where ERBB4 loss was observed, 69.1% of the loss was observed in this specific region." (PMID 29342193, 2018). "Other loci showed sample-specific variation, e.g. an ERBB4 mutation in the TM00099 tumor was confirmed by Sanger sequencing to be private to certain samples." (PMID 30560892, 2018). "ErbB4 rs1595066 creates a binding site for miR-200*, a member of miR-200 tumor-suppressor miRNAs, and is associated with a lower EC risk, probably through the downregulation of ErbB4." (PMID 30322005, 2018). "Somatic ERBB4 mutations have been reported in various cancers, and studies attempting to assess the impacts of these mutations have suggested both oncogenic and tumor suppressor functions for ERBB4." (PMID 28042953, 2017). "In our study, we identified 43 % CRC samples with ERBB4 promoter methylation which correlated with HME tumour status, MSI and BRAFV600E mutation." (PMID 25366420, 2015). "Tumor DNA samples were genotyped for ERBB4 variants and somatic mutations using matrix-assisted laser desorption ionization/time of flight mass spectrometry." (PMID 25036186, 2014). "Taken together, these findings indicate that the isoform-specific mAb 1479 can inhibit ErbB4 cleavage in vivo and that this inhibition is associated with suppression of xenograft tumor growth." (PMID 22761786, 2012). "Nevertheless, given the in vitro and in vivo observations that the anti-tumor effect of mAb 1479 was associated with its capability to suppress ErbB4 shedding, anti-ErbB4 ELISA is a promising predictive test for possible therapeutic applications of mAb 1479." (PMID 22761786, 2012). "In a recent study, loss of tumor expression of the receptor tyrosine kinase HER4/ERBB4 (referred to here as HER4) was an independent marker for tamoxifen resistance." (PMID 20550710, 2010). "It will also be important to explore whether this variant affects ERBB4 protein function, downstream signaling pathways, or tumor microenvironment interactions." (PMID 40806544, 2025).
tumor (continued). "A previous study investigated whether increased expression of the KITENIN/ErbB4 complex promotes intestinal adenoma in the tumor microenvironment associated with APC loss." (PMID 39030594, 2024). "A GWAS was performed comparing GR dogs ≥ 14 years to dogs dying prior to age 12 which revealed a significant association to ERBB4, the only member of the epidermal growth factor receptor family capable of serving as both a tumor suppressor gene and an oncogene." (PMID 37855863, 2024). "Similarly, ERBB4 is one of the members of the epidermal growth factor receptor family, which is firmly linked to cell proliferation and tumor development." (PMID 34925436, 2021). "Therefore, although ERBB4 is often associated with tumor-suppressive behavior, it has a strong oncogenic capacity that is tissue- and variant-specific." (PMID 30044378, 2018). "But sustained expression of the FL CYT-1 ERBB4 isoform resulted in the formation of neoplastic lesions/tumor in the present study, while CYT-2 expression only caused a low incidence of hyperplasia, hinting at a possible milder oncogenic predisposition of CYT-2." (PMID 25516216, 2014). "Next, we used confocal microscopy to assess whether ErbB4 mutations that disrupt the tumor suppressor activity of the constitutively-active ErbB4 Q646C EGFP-TVV construct also alter its subcellular localization." (PMID 24791013, 2013). "Therefore, the ErbB4 Q646C EGFP-TVV construct is a tool that can be used to assess the effects of ErbB4 functional motif mutations on the subcellular localization and tumor suppressor activity of the ErbB4 Q646C mutant." (PMID 24791013, 2013). "Therefore, the functional deficiencies of ERBB4 might promote tumor growth in various types of cancers, associating with the poor prognosis of cancer patients." (PMID 34620079, 2021). "Epidermal growth factor receptor (EGFR/ErbB1/HER1) and other members of the ErbB family, including ErbB2/HER2, ErbB3/HER3, and ErbB4/HER4, are receptor tyrosine kinases that play critical roles in tumor progression across various types of cancer." (PMID 40445424, 2025). "Meanwhile, Scissor- tumor cells mainly received signals through Neuregulin-ERBB4 interactions with endothelial cells, and GRN-SORT1 interactions between cDCs/mono-macrophages." (PMID 40098972, 2025). "The broader literature supports the dual nature of ERBB4 signaling in cancer, with both tumor-promoting and tumor-suppressive effects depending on the tissue context." (PMID 40806544, 2025). "The ErbB receptor family (EGFR, HER2, ErbB3, ErbB4) is expressed in lactotroph cells, promoting prolactin secretion, and inhibiting these receptors can lead to tumor regression." (PMID 41013821, 2025). "Higher mutation rates of ERBB4 and ALK in H/L patients suggest ethnicity-specific alterations in the RTK/RAS pathway, possibly linked to differential tumor biology or therapeutic response." (PMID 40869017, 2025). "AEE-788 is a dual EGFR/HER2 and VEGFR inhibitor developed to suppress tumor growth and angiogenesis; it also inhibits ERBB4 (HER4) with an IC50 of 0.16 μM, suggesting potential modulation of ERBB4 signaling." (PMID 41256885, 2025). "Further analysis of receptor-ligand interactions highlighted the roles of KNG1_BDKRB2 and NRG1_ERBB4 signaling in promoting tumor aggression, suggesting potential therapeutic targets." (PMID 40969325, 2025). "The assessment of the cancer genome profile revealed the stability of microsatellite status, a tumor mutation burden of 4 mutations per megabase (Muts/Mb), alterations in TSC1 and APC, and amplification of ERBB4." (PMID 39846235, 2025). "ERBB4 is also the only member of the EGFR family that can function as either an oncogene or a tumor suppressor gene." (PMID 37855863, 2024). "It has been discovered that the over-activation of the EGFR family of RTK, which includes EGFR (EGFR/HER-1 or ERBB-1), HER-2 (Neu or ERBB-2), HER-3 (ERBB-3), and HER-4 (ERBB-4), promotes the growth and progression of numerous tumor types." (PMID 39130630, 2024).
tumor (continued). "ERBB4 is a well-characterized receptor that acts as both a tumor suppressor and an oncoprotein in different contexts." (PMID 39489776, 2024). "ErbB4 has both oncogenic and tumor suppressor functions even if in tumors it has been more frequently observed downregulated rather than upregulated." (PMID 37371814, 2023). "ErbBs are variably expressed in different tumours; ErbB1 and ErbB2 subtypes are the most over expressed in tumours, whereas the ErbB3 and ErbB4 are the least expressed." (PMID 38203605, 2023). "In breast cancer, ErbB3 expression appears to promote tumor growth, whereas ErbB4 expression appears to perform as a weak tumor suppressor." (PMID 36768973, 2023). "CSF1R, FGFR1, FLT3, and KDR are related to the tumor microenvironment, and ERBB4, STK11, PTEN, and NPM1 are related to proliferation-related factors." (PMID 36780540, 2023). "All four members of this family, including HER1 (EGFR, ErbB1), HER2 (Neu, ErbB2), HER3 (ErbB3), and HER4 (ErbB4), play an important role in cell growth regulation, proliferation, and tumor migration." (PMID 39355049, 2023). "All 10 DEGs found in the patients who lived in Sao Paulo city compared to the MRSP were associated with cell proliferation and tumor development (BMP4, CTNNBP1, DISP1, DVL1, ERBB4, PRLR, WNT5b, LEF1, PGR, and PTEN)." (PMID 36768749, 2023). "In this cohort, one patient displayed strong ERBB3 and two patients displayed strong ERBB4 upregulation in the relapsed tumor compared to the primary tumor." (PMID 36181342, 2023). "The ERBB4+ LumA cells scarcely existed in the tumor interface, whereas LumB cells were scattered throughout the tumor." (PMID 36313703, 2022). "Circulating tumor cell clusters in GBM were first identified in 2018 and sequencing analysis identified a structural variant of the ERBB4 gene within these clusters." (PMID 36119496, 2022). "ERBB4 appeared to be altered in 17 tumor samples (53%) and 8 blood samples (25%), but this gene harbored one mutation classified as neutral and another one with no classification." (PMID 35330454, 2022). "The results of proliferation and migration experiments indicate that the balance between EGFR and ERBB4 expression shifts towards inhibiting the tumor phenotype of MCF-7 cells." (PMID 36430510, 2022). "We first compared the expression pattern of EGFR, ERBB2, ERBB3, ERBB4 in CESC tumor and normal tissues." (PMID 35581263, 2022). "It is possible that the abnormal profiled abundance of differential bacteria causes changes in the expression of PTEN, ERBB2, ERBB4, and MET and stimulates tumor growth." (PMID 35739509, 2022). "Although ERBB4 plays an essential role in different types of cancer, its role as an oncogene or tumor suppressor depends on the cellular context, and it is still under study." (PMID 36430510, 2022). "Specifically, ERBB4 has been recently found to be expressed in several tumours and tumour cell lines and its inhibition can slow tumour growth." (PMID 35379165, 2022). "ERBB4 is a tyrosine kinase receptor reported to exert both oncogenic and tumor suppressor activities." (PMID 35664762, 2022). "Intriguingly, the ERBB4 promoter appeared hypomethylated in normal tissues as well as in all clinical tumor subtypes, with minor variations." (PMID 35664762, 2022). "The RT-qPCR results suggested that the mRNA expression of ERBB4 was notably higher in the OC tumor tissues than that in the adjacent tissues, which showed a negative correlation with miR-3187-3p in OC tissues." (PMID 34774079, 2021). "In recent years, information on the role of ERBB4 in many tumors has emerged, and most studies have focused on the tumor suppressor function of ERBB4." (PMID 34630106, 2021). "RNA sequencing data from the Cancer Cell Line Encyclopedia (CCLE) has indicated that the mRNA expression of ERBB4 is down-regulated in different tumor-derived cell lines." (PMID 34620079, 2021).
tumor (continued). "ERBB4 is an important member of EGFR family whose overexpression and activation has been suggested to be associated with advanced tumor states and poor patient outcomes." (PMID 34774079, 2021). "LncRNA of UCA1 functions as an oncogene in NSCLC, acting mechanistically by upregulating ERBB4 in part through the sponging of tumor suppressor miR-193a-3p." (PMID 33628829, 2021). "ERBB3 mutations were identified in 1/40 (2.5%) HER2 negative tumours and 1/29 (3.4%) of HER2-positive tumours, while mutations in ERBB4 were identified in 2/40 (5%) HER2-negative tumours and 2/29 (6.9%) HER2-positive tumours." (PMID 33933113, 2021). "There were 26 cancer-related genes involved in these differentially affected genomic regions, including LRP1B as a putative tumor suppressor gene, and ERBB4 as a member in the EGFR subfamily of receptor tyrosine kinases." (PMID 33902690, 2021). "In summary, our work shows that ERBB4 expression is highly enriched in the pool of MBSCs, and its inactivation significantly impairs their malignant properties of proliferation and tumor initiation and progression." (PMID 32316671, 2020). "The differences in stem cell frequencies between the tested groups were statistically significant, confirming that ERBB4 inhibition limits tumor initiation and revealing an essential role for ERBB4 in MBSCs activity." (PMID 32316671, 2020). "For example, miR-203 functions as a tumor metastasis suppressor through inactivating the ERBB4/PIK3R3/mTOR/S6K2 signaling pathway, and miR-203 overexpression inhibited NSCLC metastasis in vitro and in vivo." (PMID 32206066, 2020). "It has been shown that the EGFR up regulation and ErbB4 down regulation were significantly correlated with tumor aggressiveness, advance grade, and poor overall survival in a sub population of BCa patients." (PMID 32795296, 2020). "The ambivalence of ERBB4 in PDAC, as in many other cancers, has emerged from studies assessing tumor‐suppressive functions for the receptor, in that ERBB4 expression was low in PDAC tissues and hPaCaCells and decreased in nonmetastatic tumors." (PMID 32335999, 2020). "The GNAS p.R201C, c.601C > T variant was observed in the tumor sample of patient #11, and a gene fusion [chr5:58476419(-)::chr2:212615429(-)] showing PDE4D exon 5 fused to ERBB4 exon 5 was observed in the ACT from patient #10." (PMID 32098292, 2020). "NEDD4, also known as neural precursor cell expressed developmentally downregulated protein 4, has been reported as E3 ligase for many substrates, including EGFR, PTEN, and ERBB4, and it was involved in tumor and other diseases." (PMID 31831018, 2019). "The degree of erbB4 expression was slightly variable between data sets but is supportive in the trend observed with tumor mass/volume data." (PMID 31291965, 2019). "Further, the Erbb4-null tumor cells are still NRG1-responsive, as demonstrated by our phosphorylation-specific antibody array experiments." (PMID 31291965, 2019). "Our previous analyses of two MPNST cell lines and six tumor samples indicated that erbB4 was variably expressed in these neoplasms." (PMID 31291965, 2019). "In another seven tumors, erbB4 staining was less widely distributed, with 25–50% of the tumor cells being erbB4 positive (2+)." (PMID 31291965, 2019). "Intriguingly, contrary to what was expected and published for other cancers, the ERBB4 gene is found deeply downregulated (log2(FC) = −3.67) in the HNSCC tumour samples." (PMID 31703248, 2019). "The human epidermal growth factor receptor family consists of four members: EGFR (HER1, erbB1), HER2 (erbB2, neu), HER3 (erbB3) and HER4 (erbB4), all of which regulate the proliferation and differentiation of various tumour cells." (PMID 30858756, 2019).
tumor (continued). "In conclusion, epidermal LRIG2 excess is associated with activated EGFR/ERBB4‐MAPK signaling and accelerated tumor progression in experimentally induced NMSC, suggesting LRIG2 as a potential oncoprotein in skin." (PMID 31580518, 2019). "Grafts of Erbb4-ablated tumor cells showed overall reduction in volume and mass relative to grafts of cells transduced with eGFP-expressing adenovirus." (PMID 31291965, 2019). "Although many metastatic ACC tumor samples harbored mutations in the beta-catenin gene like primary ACC, other genes involving molecular pathways such as ERBB4, GPCR, RAR, and PDGFR signaling were also frequently mutated in metastatic ACC." (PMID 30301885, 2018). "While NRG1 loss was observed in only 7 of the tumor samples from 526 GBM patients in TCGA, ERBB4 loss was observed in 81 samples." (PMID 29342193, 2018). "Both AlbT3 and A17LKO mice showed in the tumor tissue increased expression of the unclipped ErbB4 isoforms and decreased level of NRG1 suggesting that the downregulated signals mediated by this are associated to decreased tumor progression and areas." (PMID 28751722, 2017). "All 16 tumor samples exhibited greater positive cytoplasmic ERBB4 staining as compared to adjacent normal tissues." (PMID 28042953, 2017). "All the genes, apart from ERBB4, were over-expressed in grade 3 tumours compared with grade 1 tumours, and all three ERBB4 transcripts were present in the top 25 genes." (PMID 28697743, 2017). "Mutations in the RTK genes involving EGFR, ERBB2, ERBB4, FLT1 and EPHA/B, were identified in 5/7 (71%) of the H3/IDH1 wildtype tumor pairs." (PMID 29084603, 2017). "The EGFR family member, ERBB4, was expressed in fetal tumor cells from 60% of tumors, embryonal cells from 17% of HBL tumors, but absent from all SCU cells (p < 0.001, chi-square test)." (PMID 27910913, 2016). "In SK-N-MC tumor xenografts, ERBB4 and EGFR were the prominent RTKs detected by the phospho-proteome array together with INSR and IGF1R." (PMID 27374103, 2016). "Full section tumor tissue showed only faint and defined intra-tumor discrepancies for ERBB4 in low percentages of tumor tissue, but eventually these are more likely fixation artefacts than true expression differences." (PMID 26779809, 2016). "CYT-1 glandular carcinoma cells expressing ERBB4, and STAT5a, and displaying Ki-67 staining, suggest a pro-proliferative role of ErbB4 in these tumor lesions." (PMID 25516216, 2014). "Experimental studies showed that downregulation or targeting of ErbB4 suppresses the tumor progression to a great extent." (PMID 25538945, 2014). "Some studies suggest a tumor suppressor role of ERBB4, while other reports suggest an oncogenic potential." (PMID 25516216, 2014). "Histopathological examination of H&E-stained and immunostained slides showed that tumor lesions from ERBB4 CYT1 mice showed similar characteristics, with regions of hyperplasia or carcinoma with glandular or squamous differentiation or solid tumor." (PMID 25516216, 2014). "miR-302b is a potential molecular marker of ESCC and functions as a tumor suppressor by post-transcriptionally regulating ErbB4." (PMID 24438167, 2014). "Paraffin-embedded tumor sections from all patients were immunohistochemically stained for ErbB4 expression." (PMID 25036186, 2014). "Epidermal growth factor receptor belongs to the ErbB family of tyrosine kinase receptors, which includes EGFR (ErbB-1), HER-2/neu (ErbB-2), HER-3 (ErbB-3), and HER-4 (ErbB-4), all known to be involved in modulating pathways of tumor growth or proliferation." (PMID 24945674, 2014). "Nuclear ERBB4 ICD is inversely correlated with tumor grade and tumor mitosis, while cytosolic ERBB4 ICD has significant positive prognostic value in lymph node-negative breast cancer patients." (PMID 25516216, 2014).